RBIS (ribosomal biogenesis factor)
Description:
Trans-acting factor in ribosome biogenesis required for efficient 40S and 60S subunit production.
Synonyms: C8orf59
Tractability: PROTAC: ubiquitination databases record sites on it.
Gene: Protein-coding gene on chromosome 8 (85,214,048 to 85,220,793, reverse strand). Ensembl gene ENSG00000176731.
Subcellular location: Nucleus, nucleolus
Subcellular location (Human Protein Atlas): Nucleoli; Nucleoplasm; Cytosol
Gene Ontology:
Biological process: ribosome biogenesis
Cellular component: nucleolus; nucleoplasm
Genetic constraint (gnomAD): Loss-of-function variants: 0 observed, 0.35 expected, observed/expected ratio (o/e) 0, 90% interval 0 to 1.86. That is too few expected variants to judge how well the gene tolerates losing a copy. Missense variants: 4 observed, 6.97 expected, observed/expected ratio (o/e) 0.57, 90% interval 0.28 to 1.3. Synonymous variants: 3 observed, 1.97 expected, observed/expected ratio (o/e) 1.52, 90% interval 0.57 to 1.93.
Homologues: Orthologues: chimpanzee RBIS (100% identical), macaque RBIS (93% identical), dog RBIS (84% identical), pig RBIS (81% identical), mouse Rbis (77% identical), rat Rbis (76% identical), guinea pig RBIS (70% identical), rat Rbisl2 (68% identical), rat Rbisl1 (66% identical), tropical clawed frog rbis (42% identical), zebrafish rbis (37% identical).
Diseases named in the same sentence as RBIS in open-access papers:
RBIS is named in the same sentence as 3 diseases in open-access papers, as found by Europe PMC text mining. Sharing a sentence is not in itself a finding about the gene and the disease. The quoted sentences say what the papers report.
diabetic nephropathy (1 paper, 2024). "We previously reported aberrant expression of the cytosolic ribosomal biogenesis factor Nop-7-associated 2 (NSA2) in diabetic nephropathy, the latter also known to involve mitochondrial dysfunction, however the connections between NSA2, mitochondria and renal disease were unclear." (PMID 39396937, 2024).
RBIS also shares sentences with these, for which no sentence is quoted: breast carcinoma (1 paper); renal disease (1).